PDC (phosducin)
Diseases named in the same sentence as PDC in open-access papers (continued):
Sharing a sentence is not in itself a finding about the gene and the disease.
AIDS (4 papers, 2008 to 2012). A syndrome resulting from the acquired deficiency of cellular immunity caused by the human immunodeficiency virus (HIV). "One study showed that the resistance to AIDS progression in sooty mangabey model was explained by a deficient IFN-α production by pDC in response to SIV." (PMID 23243424, 2012). "However, increasing evidence suggests that IFN-α contributes to the generalized pan-immune activation and increased levels of cell apoptosis associated with AIDS progression, and thus the exact role of pDC in HIV/AIDS pathogenesis remains debatable." (PMID 19936055, 2009). "There is now a debate in the literature concerning the activation of pDC in AIDS-resistant simian models." (PMID 23243424, 2012). "Concurrently, pDC were found at higher frequency in LN of infected animals, only to decline with the onset of AIDS through a mechanism involving apoptosis." (PMID 20559432, 2010). "This study of pDC in HIV-2 infection fills a gap in the understanding of their potential role in HIV/AIDS pathogenesis." (PMID 19936055, 2009). "In this study we characterized for the first time circulating pDC in HIV-2 infected patients in order to generate insights into their role in HIV/AIDS pathogenesis." (PMID 19936055, 2009). "In contrast, it was recently shown that pDC could be activated by SIV and produce high levels of type I IFN similarly in AIDS-resistant and AIDS susceptible simian models." (PMID 23243424, 2012). "Evidence for a possible role of pDC and IFNα in AIDS pathogenesis also comes from animal models." (PMID 20559432, 2010). "Although higher pDC frequency found in long-term non-progressors indicate that pDC also have a role in HIV infection control, a possible link also exists between disease outcome and reduced pDC number and function, including a decreased production of IFN-α by pDC during AIDS progression." (PMID 18782441, 2008).
diabetes (4 papers, 2013 to 2017). "Further analysis is needed to confirm the possible association of heightened pDC activation and function with diabetes susceptibility." (PMID 27405244, 2016). "Antibody blockade of the IFNAR prior to 3 weeks of age, or depletion of pDC, delays and significantly reduces the incidence of diabetes in NOD mice." (PMID 24676425, 2014). "The role of pDC in diabetes pathogenesis is somewhat more controversial and there are conflicting reports in the literature." (PMID 24367363, 2013). "Studies in the next few years will hopefully clarify these contrasting results on the role that pDC play in diabetes pathogenesis." (PMID 24367363, 2013). "The pDC activation and type I interferon responses induced by other viruses also may modulate diabetes development." (PMID 27405244, 2016). "Furthermore these investigators showed that depletion of pDC using a depleting antibody reduced the incidence of diabetes." (PMID 24367363, 2013). "Thus, pDC activation and type I interferon-mediated bystander activation may contribute to the diabetes acceleration in RRV-infected NOD mice." (PMID 27405244, 2016). "Furthermore, pDC depletion significantly reduces diabetes incidence in NOD mice." (PMID 24676425, 2014). "When administered in vivo to prediabetic mice, the drug prevented diabetes onset through IDO1- and pDC-dependent mechanisms." (PMID 28450863, 2017). "The specificity of pDC activation was determined by analysing DC activation in RRV-infected C57BL/6 mice, which are not diabetes-prone." (PMID 27405244, 2016).
hepatocellular carcinoma (4 papers, 2023 to 2025). A malignant tumor that arises from hepatocytes. "In gastric cancer, hepatocellular carcinoma, and intrahepatic cholangiocarcinoma, higher pDC infiltration correlates with worse outcomes, whereas in esophageal, pancreatic, and colorectal cancers, it improves outcomes." (PMID 38927922, 2024). "Furthermore, PDc showed promising results in vivo with the reduction of hepatoma growth in a murine syngeneic model." (PMID 37860118, 2023). "In hepatocellular carcinoma (HCC), high pDC infiltration correlates with greater vascular invasion, an advanced stage, higher recurrence rates, and shorter survival." (PMID 41200280, 2025).
prostate carcinoma (4 papers, 2012 to 2024). A carcinoma that arises from epithelial cells of the prostate gland. "Our results showed that the expression of PCAT14 was negatively correlated with the infiltration level of pDC, aDC, Tregs, and neutrophils in prostate cancer." (PMID 35003397, 2021). "This research also found that the expression of PCAT14 is negatively correlated with the infiltration of pDC, aDC, Tregs, and neutrophils in the tumor microenvironment of prostate cancer." (PMID 35003397, 2021). "Moreover, PDC AN-207 was significantly more potent, regarding the growth inhibition of hormone-dependent Dunning R-3327-H prostate cancers in rats, reaching up to 50% of the initial tumor volume in comparison with 2-pyrrolino-DOX." (PMID 29765474, 2018). "The conjugates were evaluated regarding their antiproliferative effect on prostate cancer cells (DU145 and PC-3) and the PDC GSG showed IC50 values similar to gemcitabine GSG that possessed the highest antiproliferative effect was utilized for further pharmacokinetic studies in mice." (PMID 29765474, 2018).
chronic myelomonocytic leukemia (3 papers, 2019 to 2025). A myelodysplastic/myeloproliferative neoplasm which is characterized by persistent monocytosis, absence of a Philadelphia chromosome and BCR/ABL fusion gene, fewer than 20 percent blasts in the bone marrow and blood, myelodysplasia, and absence of PDGFRA or PDGFRB rearrangement. "This class also includes mature plasmacytoid dendritic cell proliferation (MPDCP), which is associated with myeloid neoplasms—most often chronic myelomonocytic leukemia (CMML), but also MDS, MPN, and pDC-AML (a form of AML with monocytic differentiation)—that do not express CD56." (PMID 39858003, 2025). "By extension, MPDCP associated with myelodysplastic syndrome (MDS) and chronic myelomonocytic leukemia (CMML) can be referred to as pDC-MDS and pDC-CMML." (PMID 35884612, 2022).
dengue (3 papers, 2013 to 2021). "Our group observed that IFNα and PDC activation were enhanced in mild dengue patients, and here we observed NK cell activation was also enhanced in the same patient group." (PMID 29038620, 2017). "We aimed to characterize pDC activation in dengue patients and their function under DENV-2 stimulation in vitro." (PMID 23755314, 2013). "Plasma levels of IFN-α and soluble TRAIL are increased in mild compared to severe dengue patients, positively correlating with pDC activation." (PMID 23755314, 2013). "Furthermore, dengue-infected patients had impaired pDC activation features." (PMID 23755314, 2013). "Consistent with our data, previous studies showed that only blood cDC levels but not pDC levels were inversely correlated with the severity of dengue virus infection and severe fever with thrombocytopenia syndrome." (PMID 34276693, 2021).
glomerulonephritis (3 papers, 2016 to 2022). A renal disorder characterized by damage in the glomeruli. "It was demonstrated that pDC deficiency in early disease development or the impairment of its function had beneficial effects including reduced splenomegaly, anti-nuclear autoantibody production, reduced glomerulonephritis and decreased levels of ISGs in kidney tissues." (PMID 27509492, 2016). "In addition, mice lacking E2-2, a transcription factor that regulates pDC development, display impaired pDC function, a dramatic reduction in anti-DNA autoantibody production, and glomerulonephritis as well as ameliorated disease." (PMID 26968426, 2016).
HCMV infection (3 papers, 2015 to 2021). "Although pDC expressed particularly high levels of cGAS, and the cGAS/STING axis was functional down-stream of STING, as indicated by IFN-I induction upon synthetic cGAMP treatment, pDC were not susceptible to HCMV infection and mounted IFN-I responses in a TLR9-dependent manner." (PMID 27058035, 2016).
Insulin resistance (3 papers, 2011 to 2017). Increased resistance towards insulin, that is, diminished effectiveness of insulin in reducing blood glucose levels. "Furthermore, the development of obesity and insulin resistance in this model was associated with pDC recruitment to the fatty tissues and liver of obese mice (a 4.3-fold and 2.7-fold increase, respectively)." (PMID 28660492, 2017). "Since IGF and GSK-3β are also perturbed in the brain of Guam and Japanese ALS/PDC patients, and insulin resistance is an established risk factor for dementia, the cycad genotoxins might induce tau pathology in GD and PDC by inducing brain insulin resistance." (PMID 22073019, 2011).
intrahepatic cholangiocarcinoma (3 papers, 2020 to 2024). A carcinoma that arises from the intrahepatic bile duct epithelium in any site of the intrahepatic biliary tree. "Current studies identified that the infiltration of pDC suggests that immune tolerance exists in the tumor microenvironment and pDC has the potential to be a great prognostic factor for intrahepatic cholangiocarcinoma." (PMID 36676763, 2023). "Peritumoral pDC infiltration may indicate an immune tolerogenic peritumor microenvironment and can be used to predict a poor prognosis for patients undergoing curative resection for intrahepatic cholangiocarcinoma." (PMID 33292317, 2020).
Listeria infection (3 papers, 2009 to 2012). "To evaluate the contribution of pDC to the overall IFN production in vivo after Listeria monocytogenes infection, we performed depletion experiments." (PMID 21494554, 2011). "By extrapolation, a contribution of pDC to the type I IFN response after systemic Listeria infection could be expected, although in vitro stimulation of splenic pDC with Listeria did not induce type I IFN." (PMID 21494554, 2011). "To further rule out pDC as major producers of IFN-I during Listeria infection of mice and to confirm a prominent role of myeloid cells, we purified cell populations from L. monocytogenes infected spleens by FACS and measured IFN-I production by RT-PCR." (PMID 19325882, 2009).
lymphoma (3 papers, 2015 to 2025). A malignant (clonal) proliferation of B- lymphocytes or T- lymphocytes which involves the lymph nodes, bone marrow and/or extranodal sites. "Moreover, EBV-induced lymphoma formation was observed after pDC depletion, and this was mediated by decreased NK cells." (PMID 40461625, 2025).
Obesity (3 papers, 2015 to 2022). Accumulation of substantial excess body fat. "We also analysed pDC, the major type I IFN-producing cellular subset, activity accumulated in the liver and AT during DIO and the effects of induced pDC deficiency on the development of obesity and metabolic abnormalities." (PMID 28660492, 2017). "Along with an increase in chemokines exercise treatment partially restored the obesity-related decrease in BAL macrophages, pDC, TipDC, neutrophils, and monocytes." (PMID 26110868, 2015).
retinoblastoma (3 papers, 2017 to 2025). A malignant tumor that originates in the nuclear layer of the retina. "Interestingly, the level of expression of UBE2C, EBF3, GAP43, and PDC was reminiscent of a profile of non-proliferative subtype 1 retinoblastoma (cluster 1 population), also cited in previous studies as cone precursors and cone precursor-like." (PMID 40898088, 2025). "Since Y79 photoreceptors were originally derived from a human retinoblastoma, they may not act as normal human photoreceptors in vitro in every respect although they express several markers of differentiated photoreceptors including opsin, arrestin, phosducin and IRBP." (PMID 28257068, 2017).
allergic dermatitis (2 papers, 2020 to 2025). "Moreover, byakkokaninjinto is anticipated to be used as a therapeutic agent for pDC-related diseases, such as allergic dermatitis." (PMID 33149758, 2020).
allergic disease (2 papers, 2018 to 2021). An immune response that occurs following re-exposure to an innocuous antigen, and that requires the presence of existing antibodies against that antigen. "Further studies are required to shed more light into the long-time underestimated role of pDC in allergic disease and tolerance induction." (PMID 34789269, 2021). "In summary, our findings strengthen previous observations suggesting a more prominent role of pDC in allergy pathogenesis than generally anticipated." (PMID 34789269, 2021).
Alzheimer disease (2 papers, 2014 to 2018). A progressive, neurodegenerative disease characterized by loss of function and death of nerve cells in several areas of the brain leading to loss of cognitive function such as memory and language. "L-BMAA, an amino acid not derived from proteins, was first implicated with the heightened occurrence of ALS/PDC on the small island of Guam and was considered as a potential environmental factor in neurodegenerative diseases including ALS and Alzheimer’s disease." (PMID 30476904, 2018). "Reports of BMAA in the brain of deceased patients suffering from ALS, PDC, or Alzheimer’s disease support the BMAA ALS/PDC hypothesis, however, these results could not be replicated by another research group." (PMID 24662480, 2014).
Chlamydia pneumonia (2 papers, 2015 to 2017). "Some studies have suggested that pDC is more potent to induce pro-inflammatory cytokines and modulate non-protective T-cell responses; Others indicate that in Chlamydia pneumonia lung infection model, depletion of pDCs increased the severity of infection and lung pathology." (PMID 29552679, 2017).
colon cancer (2 papers, 2022 to 2024). "Contradictory observations have been made regarding pDC and survival prognosis in human colon cancer." (PMID 36189323, 2022).
fungal infection (2 papers, 2016 to 2022). "The severity of fungal infection in pDC-depleted and control groups of P. brasiliensis infected mice was then assessed at early and late periods of the disease by CFU counts, tissue pathology and mortality rates." (PMID 27992577, 2016). "Given the functional diversities and physiological relevance of cDC1, cDC2 and pDC subsets in generating immunity against bacterial, viral, and fungal infections, it would be of major clinical significance to study DC physiology in TBI patients, especially in individuals with immune insults." (PMID 36183126, 2022).
glaucoma (2 papers, 2008 to 2021). Increased pressure in the eyeball due to obstruction of the outflow of aqueous humor. "These 13 glaucoma-associated genes can be divided into three functional groups: phototransduction-related genes (GNGT1, OPN1SW, PDE6A, PDC, CRX, CNGB1, GUCY2F), glutamate receptor (GR) genes (GRIN2B, GRIK3, GRIK4), and 5-hydroxytryptamine receptor (HTR) genes (HTR1A, HTR1E, HTR7)." (PMID 33874942, 2021).
herpesvirus infections (2 papers, 2009 to 2015). "Here, we summarize and discuss current knowledge regarding pDC implication in the physiopathology of mouse and human herpesvirus infections, and we discuss how pDC functions could be manipulated in immunotherapeutic settings to promote health over disease." (PMID 21994554, 2009). "This raises the question of whether the pDC deficiency reported in certain patients with severe herpesvirus infections could be a consequence rather than a cause of the disease." (PMID 21994554, 2009). "However, these pDC functions have not yet been examined in vivo during herpesvirus infections." (PMID 21994554, 2009).
Hyperglycemia (2 papers, 2022). An increased concentration of glucose in the blood. "More evidence also found PDC activity decreased in leptin receptor-deficient mice and increased PDC phosphorylation in cardiomyocytes under hyperglycemia." (PMID 35783195, 2022). "In type 2 diabetes, up-regulation of PDK4 also inactivates PDC, which promotes gluconeogenesis and thereby contributes to the hyperglycemia characteristic of this disease." (PMID 35642195, 2022).
Hypertension (2 papers, 2011 to 2020). The presence of chronic increased pressure in the systemic arterial system. "PDC, encoding a phosphoprotein involved in the process of vision in the retina, has been associated with stress-induced hypertension." (PMID 33076555, 2020). "Sumoylation of phosducin inhibits postganglionic sympathetic neuron activity and prevents stress-induced hypertension." (PMID 21390240, 2011).
metastatic melanoma (2 papers, 2013 to 2024). A melanoma that has spread from its primary site to another anatomic site. "The efficacy of pDC has been verified in a cohort of metastatic melanoma patients in whom activated pDC were found to induce Ag-specific T-cell responses and significantly extended overall survival." (PMID 24400008, 2013).
Pancreatic cancer (2 papers, 2021 to 2023). "PDC, TFH, Tgd, cytotoxic cells, B cells and Th17 cells were negatively associated with BHLHE40 levels in pancreatic cancer." (PMID 37773521, 2023).
retinal degeneration (2 papers, 2023 to 2024). Degeneration of the retina. "PDC modulates G-protein-coupled receptor signaling, and Prom1 mutations link to retinal degeneration." (PMID 39534499, 2024).
triple-negative breast carcinoma (2 papers, 2020 to 2024). An invasive breast carcinoma which is negative for expression of estrogen receptor (ER), progesterone receptor (PR), and human epidermal growth factor receptor 2 (HER2). "We found that high pDC was significantly associated with better survival in triple negative breast cancer (TNBC), but not cDC." (PMID 33198125, 2020). "We found that triple-negative breast cancer (TNBC) had a high fraction of cDC and pDC compared to the other subtypes." (PMID 33198125, 2020).
bacterial pneumonia (1 paper, 2013). Acute infection of the lung parenchyma caused by bacteria (e.g., Streptococcus pneumoniae, Haemophilus influenzae, Chlamydia pneumoniae, Mycoplasma pneumoniae, and Legionella pneumophila). "With respect to the novel finding of increased pDC during Klebsiella infection, future studies are necessary to address the functional role of pDC during bacterial pneumonia." (PMID 24044871, 2013). "We confirmed the identity of functional respiratory pDC during bacterial pneumonia by extended phenotyping and demonstration of large IFN-alpha production capacity after cell sorting." (PMID 24044871, 2013). "Alternatively, accumulation of pDC in the post acute bacterial pneumonia phase may be related to immunoregulatory functions of these cells." (PMID 24044871, 2013). "The detection of increased respiratory pDC numbers in bacterial pneumonia may indicate possible novel pDC functions with respect to lung repair and regeneration." (PMID 24044871, 2013). "The accumulation of functional respiratory pDC during bacterial pneumonia has to the best of our knowledge not been reported so far and raises the question regarding potential novel functions of pDC in bacterial pneumonia." (PMID 24044871, 2013).
bacterial sepsis (1 paper, 2021). "Their indispensability to immune competence is highlighted by experimental studies using conditional pDC deletion system that shows pDC-dependent survival from burns and by survival studies in experimental bacterial sepsis." (PMID 34341701, 2021).
blastic plasmacytoid dendritic cell neoplasm (1 paper, 2015). "CD4+CD56+ hematologic malignancy with primary cutaneous presentation has been well documented and is proposed as the malignant counterpart of pDC precursors and was named as blastic plasmacytoid dendritic cell neoplasm (BPDCN)." (PMID 25779340, 2015).
Blindness (1 paper, 2021). Blindness is the condition of lacking visual perception defined as a profound reduction in visual perception. "Several previous studies indicated that defects of CRX or PDC might answer for photoreceptor degeneration, leading to cone swelling and loss of photoreceptor cells, and eventually causing blindness." (PMID 33874942, 2021).
cervical cancer (1 paper, 2011). A primary or metastatic malignant neoplasm involving the cervix. "In humans, pDC are present in cervical cancer lesions, primarily in the stroma underlying the tumor rather than the dysplastic epithelium, and produce the anti-viral cytokine, IFN-α, in response to HPV VLP." (PMID 24212964, 2011).